IL18 (interleukin 18)
Diseases named in the same sentence as IL18 in open-access papers (continued):
Sharing a sentence is not in itself a finding about the gene and the disease.
cystic fibrosis (2 papers, 2007 to 2024). Autosomal recessive disorder caused by pathogenic variants in the CFTR gene (cystic fibrosis transmembrane conductance regulator), which encodes a chloride and bicarbonate channel expressed in epithelial cells, and follow the diagnosis criteria. "Studies of cystic fibrosis patients positive for Pseudomonas aeruginosa showed that BALF and leukocytes obtained from the BALF exhibit decreased levels of IL-18 compared to healthy control patients." (PMID 17352829, 2007).
cystitis (2 papers, 2023 to 2025). Inflammation of the urinary bladder. "The cystitis was associated with enhanced bladder mRNA expression levels of the inflammatory cytokines, Cxcl10, Ccl2, Il18, Tgfb, and Tnfa." (PMID 35647939, 2023).
diabetic neuropathy (2 papers, 2017 to 2026). A chronic, pathological complication associated with diabetes mellitus, where nerve damages are incurred due to diabetic microvascular injury involving small blood vessels that supply these nerves, resulting in peripheral and/or autonomic nerve dysfunction. "Prolonged IL-18 elevation can damage neurons, both directly and indirectly, including in diabetic neuropathy." (PMID 28531131, 2017).
endometritis (2 papers, 2022 to 2025). An acute or chronic, usually bacterial infectious process affecting the endometrium. "We speculate that caspase 4 may be activated by NETs during endometritis and cleave pro-IL-1β, pro-IL-18, and GSDMD to induce pyroptosis." (PMID 36430491, 2022). "The results showed that the mRNA levels of IL-1β, IL-6, IL-8, and IL-18 were significantly reduced in the drug treatment groups compared to the LPS group, which is consistent with results from other studies using TCMF treatments for endometritis." (PMID 41002185, 2025). "Since IL-1β and IL-18 are the final cytokines in the pyroptosis pathway, the significant inhibition of LPS-induced IL-1β and IL-18 mRNA levels by TCMF suggests that their anti-endometritis mechanisms may be related to pyroptosis, which warrants further investigation." (PMID 41002185, 2025).
enteropathy (2 papers, 2018 to 2020). "If confirmed, they would suggest that IL-18 plays an important role in HIV-induced enteropathy and should be considered a target molecule for reducing HIV-induced pathology." (PMID 29601578, 2018). "Our results suggest that the virus-induced IL-18 plays an important role in the enteropathy observed in HIV-infected individuals." (PMID 29601578, 2018).
epileptic seizure (2 papers, 2015 to 2025). "The purpose of this study is to characterize the regional and temporal expression of IL −18 and related factors in the brain following SE in a rat GD seizure model followed by localization of IL-18 to specific cell types." (PMID 26203299, 2015). "In the present study, econazole effectively reduced TRPV5 expression in activated microglia following epileptic seizure and LPS stimulation, and further induced the disruption of AKT/NF‐κB activation, NLRP3 inflammasome complex assembly, and the production of proinflammatory cytokine IL‐18." (PMID 40708193, 2025).
Fabry disease (2 papers, 2016 to 2017). Fabry disease (FD) is a progressive, inherited, multisystemic lysosomal storage disease characterized by specific neurological, cutaneous, renal, cardiovascular, cochleo-vestibular and cerebrovascular manifestations. "The mechanisms underlying the upregulation and elevated secretion of IL-18 in FC-iPSC-CMs were assessed, and one of possible cause was the reduced expression and activity of GLA in Fabry disease." (PMID 27888626, 2016).
fascioliasis (2 papers, 2020 to 2021). A parasitic infection that is caused by liver flukes, usually Fasciola hepatica, of sheep, goats, and cattle. "Cattle with Fascioliasis only, had significantly higher serological levels of IFN-γ, IL-1, IL-2, IL-4, and IL-18 than control and CE single infected cattle." (PMID 32915902, 2020).
glomerular diseases (2 papers, 2020 to 2022). "NLRP3 inflammasome was activated in tubulointerstitial and glomerular diseases, promoting proinflammatory cytokines IL-1β and IL-18 production and excretion, causing renal inflammatory injuries." (PMID 32116724, 2020). "IL-18 has reported to express in different types of renal cells such as tubular epithelial cells, intercalated cells, and tubulointerstitial cells as well as mesangial cells in lupus nephritis (LN) and participates in the pathogenesis of tubular and glomerular diseases." (PMID 36379914, 2022). "IL-18 promotes clinically relevant AKI induced by sepsis, nephrotoxins, and ischemia/reperfusion injury and glomerular diseases, as well as unilateral ureteric obstruction (UUO)." (PMID 36379914, 2022).
hay fever (2 papers, 2006 to 2015). "The observed associations between the IL18 SNP and hay fever or atopy are consistent with IL18 being a determinant of TH1 and TH2 differentiation." (PMID 16759385, 2006). "In the large, well-characterized SAPALDIA cohort the IL6(-174G>C) and IL18(-137G>C) polymorphisms were associated with circulating total IgE concentrations in subjects with hay fever." (PMID 16759385, 2006). "For the IL18(-137G>C) SNP, we observed a statistically significant association with the risk of hay fever for heterozygous carriers compared to homozygous GG genotypes (OR: 1.24, 95% CI: 1.07 – 1.43, P = 0.004)." (PMID 16759385, 2006). "However among hay fever cases IL18(-137) CC genotype was associated with increased total IgE levels (P = 0.01)." (PMID 16759385, 2006). "The IL18(-137G>C) polymorphism was also associated with the prevalence of hay fever." (PMID 16759385, 2006).
head and neck cancer (2 papers, 2019 to 2025). A primary or metastatic malignant neoplasm affecting the head and neck. "Studies on head and neck cancer (HNC) have shown a connection between IL18 genetic variation and a predisposition to developing cancer." (PMID 41257666, 2025).
Hepatosplenomegaly (2 papers, 2021 to 2025). Simultaneous enlargement of the liver and spleen. "In addition to extensive hemoglobin consumption, IL-18 release causes sinusoidal dysfunction with further cytopenia and hepatosplenomegaly." (PMID 41306170, 2025).
Histiocytosis (2 papers, 2008 to 2014). An excessive number of histiocytes (tissue macrophages). "However, the analysis also revealed a more intense histiocytosis in lymph nodes (LNs) obtained from IL-12-treated mice compared to IL-12+IL-18-treated mice." (PMID 24587231, 2014). "Even though we did not observe differences in histiocytosis when comparing the livers of IL-12 and IL-12+IL-18 mice, previous results confirmed that sera levels of the hepatic enzymes ALT and aspartate aminotransferase (AST) were significantly higher in IL-12-treated mice." (PMID 24587231, 2014).
histoplasmosis (2 papers, 2021 to 2025). A disease caused by the fungus Histoplasma capsulatum. "Significant differences in the median values of IL-1β, TNF-α, IFN-γ, IL-18, IL-17A, IL-33, IL-13, and CXCL8 were reached in all the groups studied, suggesting that these cytokines play a role in the inflammatory processes associated with histoplasmosis and pneumocystosis." (PMID 34829225, 2021). "Elevated IL-1β, TNF- α, IL-18, and PTX3 levels in HIV patients with histoplasmosis could serve as a potential predictive biomarker for poor prognosis and disseminated disease development in these individuals." (PMID 40558960, 2025). "In our study, TNF-α and IL-1β together with IL-6 and IL-18 showed the highest values, with statistical differences for the group of HIV patients and Hc suggesting that these cytokines play a role in the local inflammatory processes of histoplasmosis in HIV patients." (PMID 40558960, 2025). "Significant differences in median values of SP-A, IL-1β, TNF-α, IFN-γ, IL-18, IL-17A, IL-33, IL-13, and CXCL8 were found among all the groups studied, suggesting that these cytokines play a role in the local inflammatory processes of histoplasmosis and pneumocystosis." (PMID 34829225, 2021).
hypersensitivity reactions (2 papers, 2012 to 2022). "Interleukin-18 is a proinflammatory biomarker produced by macrophages and is increased in other types of hypersensitivity reactions in people, therefore it was included in this study for its potential as a discriminatory biomarker." (PMID 36003410, 2022).
hypertensive nephropathy (2 papers, 2022 to 2025). Kidney damage that results from chronically elevated blood pressure; complications include glomerular damage resulting in proteinuria and hematuria. "In elderly individuals with hypertensive nephropathy, elevated levels of NGAL, KIM-1, IL-18, TNF-α, IL-6, NF-κB, and FMO3 were observed, accompanied by reduced urinary TMAO concentrations and impaired renal function, as indicated by increased serum creatinine and decreased eGFR." (PMID 40978750, 2025).
infectious mononucleosis (2 papers, 2022 to 2024). A condition characterized by an increase in mononuclear white blood cells and swollen lymph nodes, which is usually caused by infection with the Epstein-Barr virus. "Concerning the activation of inflammasomes in EBV-related illnesses, the onset of EBV-induced infectious mononucleosis results in an upsurge of IL-18 levels in plasma and a substantial increase in IL-18 within lymphoid tissue." (PMID 38590522, 2024). "Ebv-induced infectious mononucleosis results in elevated levels of IL-18 in plasma and maintains the expression of EBV-dissolving switch ZEBRA via NLRP3, thus promoting the replication and release of virions." (PMID 38590522, 2024). "Regarding inflammasome activation in EBV-related diseases, EBV-induced infectious mononucleosis leads to elevated IL-18 levels in plasma and substantial amounts of IL-18 in lymphoid tissues." (PMID 35038917, 2022).
itch (2 papers, 2017 to 2024). "Given that Nlrp3-knockout (KO) mice exhibited increased scratching behavior in a DNFB-induced chronic itch model, we further investigated whether IL-18 or IL-1β plays a vital role in NLRP3 inflammasome activation." (PMID 39867900, 2024). "Associations were also demonstrated with disease extent and IL-18 (an APC cytokine; B = 0.438, p = 0.001), TGF-β (a Treg cytokine; B = −0.015, p = 0.001) and IL-23 (B = −2.812, p = 0.006); pruritus and IL-23 (an APC cytokine, B = 0.387, p = 0.007); TEWL and IL-18 (B = 0.040, p = 0.010)." (PMID 28216598, 2017). "The present study found that the plasma concentration of IL-18 positively correlated with the extent or area of the disease, whereas IL-23, also an APC cytokine, negatively correlated with the extent but positively with pruritus." (PMID 28216598, 2017).
joint disease (2 papers, 2020 to 2022). "s-JIA/AOSD patients with an IL-6–dominant pattern (s-JIA:IL-18/IL-6 <1000, AOSD IL-18/IL-6 <5000) had more severe joint disease, whereas those with an IL-18–dominant pattern (s-JIA:IL-18/IL-6 >1000) had a more severe systemic disease and developed MAS." (PMID 36211331, 2022).
juvenile dermatomyositis (2 papers, 2022 to 2023). Juvenile dermatomyositis (JDM) is the early-onset form of dermatomyositis (DM), a systemic, autoimmune inflammatory muscle disorder, characterized by proximal muscle weakness, evocative skin lesion, and systemic manifestations. "Indeed, IL-18 levels were found to be significantly elevated in patients with sJIA compared to those with Kawasaki disease, TNF Receptor-associated periodic syndrome (TRAPS), SLE, juvenile dermatomyositis (JDM), and hematological conditions such as leukemia." (PMID 37446301, 2023).
lepromatous leprosy (2 papers, 2020 to 2023). A chronic communicable infection which is a principal or polar form of leprosy. "In addition, were observed lowexpression of caspase-1, interleukin-1β, and interleukin-18 in tuberculoidand lepromatous leprosy." (PMID 32130367, 2020). "NLRP3 inflammasome’s immunohistochemical strong expression score is ahallmark of the Lepromatous Leprosy - The immunohistochemicalexpression of NLRP3, caspase-1, caspases-4/5, IL-1β, IL-6, and IL-18 between thegroups presented statistically significant differences in the scores." (PMID 32130367, 2020).
macular degeneration (2 papers, 2018 to 2025). Loss of vision in the central portion of the retina (macula), secondary to retinal degeneration. "At the same time, the AUC values of IL-1β and IL-18 were determined to be 0.8089 and 0.7838 by ROC curve analysis, indicating their utility as peripheral blood biomarkers in diagnosing macular degeneration." (PMID 40837366, 2025). "In the future, cell experiments and other methods should be used to clarify the precise regulatory pathways involving NLRP6, IL-1β and IL-18 in macular degeneration." (PMID 40837366, 2025). "Our findings show that the levels of NLRP6, IL-1β and IL-18 in the peripheral blood of patients with macular degeneration are increased." (PMID 40837366, 2025).
mantle cell lymphoma (2 papers, 2023 to 2024). Mantle cell lymphoma is a rare form of malignant non-Hodgkin lymphoma affecting B lymphocytes in the lymph nodes in a region called the ``mantle zone''. "Using high-density microarray chips, differential gene expression analysis in mantle cell lymphoma (MCL) demonstrated an upregulation of the IL-18 gene." (PMID 38397043, 2024). "For instance, β-catenin can inhibit the nuclear transcription of NF-κB and can, therefore, suppress the production of cytokines, such as IL-6, IL-18, and IL-1β, in mantle cell lymphoma (MCL)." (PMID 37189739, 2023).
mental disorder (2 papers, 2024). A disease that has its basis in the disruption of mental process. "Compared to common cytokines like INF-γ, IL-6, and TNF-a, NLRP3 and IL-18 have rarely been studied in clinical studies of mental disorders." (PMID 38627683, 2024).
mesothelioma (2 papers, 2014 to 2023). A usually malignant and aggressive neoplasm of the mesothelium which is often associated with exposure to asbestos. "This was verified by Vδ2 T/mesothelioma co-culture experiments demonstrating membrane ballooning morphology, increased cleaved caspase-3 and gasdermin E, and upregulated IL-1β and IL-18." (PMID 38077396, 2023). "Interestingly, live-imaging of Vδ2 T cells co-cultured with mesothelioma showed the induction of pyroptosis in the cells, which was confirmed by the detection of the active Caspase 3 and gasdermin E protein expressoion, as well as increased IL-1β and IL-18." (PMID 38077396, 2023). "Taken together, Vδ2 T cells can induce pyroptosis in mesothelioma cells via the canonical pathway but only induce active IL-18 and IL-1β in MSTO-luc but not H2052-luc cells, which may suggest the higher resistance of H2052-luc cells towards Vδ2 T cell killing." (PMID 38077396, 2023). "Further studies are in progress to offer an understanding of how asbestos-induced activation of the inflammasome and subsequent generation of biomolecules (IL-1β, IL-18, HMGB1 etc.)may lead to mesothelial cell transformation events and mesothelioma development." (PMID 24885895, 2014).
mood disorder (2 papers, 2023 to 2025). A cognitive disorder a disturbance in which the person's mood is hypothesized to be the main underlying feature. "Additionally, IL-18 is linked to mood disorders and cognitive dysfunction, which are common symptoms in SZ." (PMID 39940697, 2025).
Multiple Organ Failure (2 papers, 2013 to 2022). A progressive condition usually characterized by combined failure of several organs such as the lungs, liver, kidney, along with some clotting mechanisms, usually postinjury or postoperative. "As such, blocking production of IL-18 is also a way of preventing multiple organ failure during the onset of SAP." (PMID 23983797, 2013).
Myalgia (2 papers, 2021 to 2025). "Among the cytokines involved, IL-18 was a significant predictor of active AOSD and its myalgia." (PMID 34367188, 2021).
myopia (2 papers, 2008 to 2023). "In conclusion, the intraperitoneal injection of MCC950 can attenuate the progression of myopia in FDM by downregulating the expression levels of NLRP3 and its downstream signaling pathway factors (IL-1β, IL-18, Caspase-1, and MMP-2)." (PMID 37958819, 2023).
neonatal-onset multisystem inflammatory disease (2 papers, 2022). "This is best demonstrated in conditions where genetic mutation in inflammasome components lead to aberrant IL-1 and IL-18 signalling, including familial mediterranean fever, cryopyrin-associated periodic syndrome, and neonatal-onset multisystem inflammatory disease (NOMID)." (PMID 38566906, 2022). "However, overproduction of IL-18/1β and NLRP3 leads to neonatal-onset multisystem inflammatory disease (NOMID) which damages the spleen, skin, liver, and bone a lot." (PMID 36091247, 2022).
obesity syndrome (2 papers, 2020 to 2025). "To evaluate the contribution of the NLRP3 inflammasome and its downstream effectors IL-1 and IL-18 in this process, we applied the true-to-life “American lifestyle-induced obesity syndrome” (ALiOS) diet mouse model." (PMID 33202693, 2020).
obstructive uropathy (2 papers, 2012 to 2024). "IL-18, besides its inflammatory role, emerges as a biomarker for kidney injury, with high serum levels associated with conditions like tubular necrosis and delayed graft function, indicating its involvement in kidney pathology induced by diverse disease processes, including urinary obstruction." (PMID 39061823, 2024).
Oral Squamous Cell carcinoma (2 papers, 2021 to 2022). "For instance, in Oral Squamous Cell carcinoma (OSCC), IL-37 inhibited the proinflammatory effects of IL-18 and the increased IL-18/IL-37 ratio in serum predicted shorter overall and disease-free survival." (PMID 35211118, 2022).
ovarian tumor (2 papers, 2020 to 2025). "In some cases, such as for IL18, immune cells stained intensely by immunohistochemistry while ovarian tumor cell cytoplasm stained moderately." (PMID 31923221, 2020). "The study objective was to determine if the NLRP3 inflammasome components (NLRP3, caspase-1), and the corresponding cytokine products, IL1β and IL18, were increased in ovarian tumors." (PMID 31923221, 2020). "Similar to the chicken, CASP1 (2.7x; p = 0.05), IL1β (4.9x; p = 0.04) and IL18 (33x; p = 0.02) mRNA were significantly higher in human ovarian tumors." (PMID 31923221, 2020). "The Human Protein Atlas suggests human ovarian tumors express NLRP3, caspase-1, IL1β and IL18." (PMID 31923221, 2020).
pancreatic diseases (2 papers, 2020 to 2024). "Recent studies have elucidated the involvement of IL-18 in pancreatic disorders, presenting novel opportunities for therapeutic strategies that target this cytokine." (PMID 38784040, 2024).
peripheral arterial occlusive disease (2 papers, 2018 to 2022). "Further research is required to fully elucidate the role of IL-18 and its genetically related pathways in vascular occlusive diseases." (PMID 29485097, 2018).
peripheral vascular disease (2 papers, 2014 to 2023). Any disorder affecting blood flow through the veins or arteries outside of the heart. "IL-18 is elevated in the patients with PAH and there is evidence that abnormal levels of IL-18 play a role in vasculopathy of the pulmonary circulation." (PMID 24739042, 2014).
pharyngitis (2 papers, 2022 to 2024). Inflammation of the throat most often caused by viral and bacterial infections. "In general, myeloid cells are the primary sources of IL-1β and IL-18 and elevated levels of both cytokines were found locally and systemically in a pharyngitis human challenge trial as well as increased frequencies of circulating monocytes and DCs." (PMID 38408992, 2024).